CRP (C-reactive protein)
Diseases named in the same sentence as CRP in open-access papers (continued):
Sharing a sentence is not in itself a finding about the gene and the disease.
pericardial effusion (continued). "At day 10 of hospitalization, our patient had classical signs of cardiac tamponade with a voluminous pericardial effusion seen on echocardiographic examination and elevated C-reactive protein, compatible with a diagnosis of constrictive pericarditis." (PMID 35945602, 2022). "CRP was 2.8 mg/dl (normal limits < 0.7 mg/dl) and imaging (echocardiography) revealed small pericardial effusion." (PMID 34809625, 2021). "In fact, a younger age as well as an increased C-reactive protein and pericardial effusion at admission were more frequent in patients who recovered compared with those who did not." (PMID 30921422, 2019). "Even if some studies are suggesting that pericardial effusion is a result of a severe inflammatory process and cytokine storm in the studied group, we found a significant statistical correlation only with CRP, PAI, and ESR values." (PMID 38999316, 2024). "In addition to the evaluation by logistic regression, the Spearman correlation test demonstrated a correlation of pericardial effusions with CRP levels." (PMID 36013560, 2022). "The patient fulfilled two out of four major criteria (pericardial chest pain and new pericardial effusion), along with one of the additional supporting findings (elevated CRP, white blood cells and erythrocyte sedimentation rate), rendering the diagnosis of pericarditis evidence-based." (PMID 34809625, 2021). "We observed multiple highly significant positive correlations between absolute neutrophil count and markers of inflammation (CRP), cardiac dysfunction (presence of pericardial effusion, levels of troponin, creatine kinase, and NTpro-BNP) and overall length of hospital stay." (PMID 34632327, 2021). "However, changes in objective measures such as CRP, pericardial inflammation by cardiac MRI and pericardial effusion by cardiac MRI and echocardiography support efficacy." (PMID 33229362, 2020). "In general, according to the European Society of Cardiology, the follow-up of pericardial effusion is mainly based on the evaluation of symptoms and the echocardiographic size of the effusion, as well as additional features such as inflammatory markers (e.g. CRP)." (PMID 40658121, 2025). "High CRP levels in IRAP at onset are associated with major in-hospital cardiac complications, such as cardiac tamponade, non-obstructive cardiogenic shock, ventricular tachycardia, large symptomatic pericardial effusion requiring pericardiocentesis or pericardiectomy, up to death." (PMID 39798014, 2025). "Moreover C-reactive protein (CRP), pleural and pericardial effusions remained unchanged." (PMID 34809625, 2021). "The patient was found to have elevated troponin, CRP, and ESR; pericardial effusion along with a Coxsackie A virus titer of 1:800, suggestive of Coxsackie A virus–induced recurrent myopericarditis." (PMID 39610985, 2024). "Patients presented with similar rates of pre-operative C-reactive protein (CRP), creatinine, platelet lymphocyte ratio (PLR), aortic regurgitation, LEVF, pericardial effusion, ascending aortic diameter (p > 0.05)." (PMID 35903673, 2022). "Patients with pericardial effusion had higher respiratory rates, coagulation parameters (D-dimers, PAI-1), leukocytes, inflammatory parameters (CRP, serum ferritin), and cardiac markers (myoglobin, CK, CK-MB, BNP, and LDH)." (PMID 36013560, 2022). "All had CRP levels <1 mg/dL, absent pericardial rub, normal electrocardiogram, and no pericardial effusion." (PMID 38471825, 2024). "Furthermore, patients with pericardial effusions showed elevated levels of cardiac enzymes (myoglobin, CK, and CK-MB), LDH, platelets, and CRP, along with a higher mortality rate." (PMID 38999316, 2024). "The patient was initially treated with ibuprofen (600 mg, administered three times daily) and colchicine (0.5 mg once daily), resulting in positive clinical response, resolution of chest pain, improvement in TTE findings (trace pericardial effusion), normalization of ECG, and CRP (0.4 mg/dL)." (PMID 39458001, 2024).
pericardial effusion (continued). "For the testing set, patients with NOAF also had higher age and c-reactive protein level, and a higher proportion of male, smoking history, centric pulmonary carcinoma, and pericardial effusion (all P<0.05), compared with patients without NOAF." (PMID 37519821, 2023). "In these scores, age > 5 years, GI involvement, headache, pericardial effusion, D-dimer > 607 ng/ml, low platelets, elevated CRP, and the absence of rash or mucocutaneous lesions were the main predictors of MIS-C." (PMID 36409406, 2022). "In the COPPS-2 trial, colchicine administration starting before surgery failed to prevent postoperative pericardial effusion in the whole study cohort but was efficacious in patients with higher CRP." (PMID 31477020, 2019). "According to the relevant literature, elder age (>5 years), gastrointestinal (GI) system involvement, headache, pericardial effusion, elevated levels of d-dimer and C-reactive protein (CRP), low platelet count, and absence of rash were the main predictors of MIS-C." (PMID 37371276, 2023). "All 28 patients had a CRP concentration <1 mg/dL, normal ECG, no pericardial rub, and no pericardial effusion at the 18MDM." (PMID 39172552, 2024). "The patient is still well under this treatment, asymptomatic, with normal CRP and WBC, and no pericardial effusion on serial transthoracic echocardiogram assessment." (PMID 39458001, 2024).
renal cell carcinoma (59 papers, 2004 to 2026). "The association between CRP and renal cell carcinoma has been studied often in the last decade, including intratumoral CRP expression and preoperative or pre-therapeutic CRP levels as a biomarker for survival." (PMID 37552264, 2023). "The association of CRP and CTCs was recently evaluated in a renal cell carcinoma study, further demonstrating a strong correlation of both parameters with coagulation." (PMID 34884980, 2021). "Growing evidence has revealed that pretreatment C-reactive protein to albumin ratio (CAR) are associated with prognosis for patients with renal cell carcinoma (RCC)." (PMID 31644587, 2019). "Elevated high sensitivity (hs-CRP) levels have been associated with increased mortality in breast, lung and renal cell carcinomas." (PMID 30138391, 2018). "Interestingly, in renal cell carcinoma higher CRP was associated with a stronger infiltration with CD8+, FoxP3+ and CD163+ cells and subsequently with worse prognosis." (PMID 31788452, 2019). "Background/Objectives: To evaluate the utility of the addition of C-reactive protein/albumin ratio (CAR) to the International Metastatic Renal Cell Carcinoma Database Consortium (IMDC)." (PMID 42122209, 2026). "The role of the c-reactive protein to albumin ratio (CAR) as a predictor of poor prognosis in renal cell carcinoma (RCC) remains insufficiently recognized." (PMID 41566198, 2026). "In 2023, a group of researchers compared the CRP group definitions of Fukuda and Ishihara in a larger number of patients with renal cell carcinoma." (PMID 39001486, 2024). "At least for the renal cell carcinoma entity for which the earlier CRP group definition was established, CRP kinetic, therefore, appears to have prognostic significance." (PMID 39001486, 2024). "Nevertheless, the baseline CRP level in the HNSCC collective showed a significantly wider spread than in the renal cell carcinoma collective (0–118 mg/L vs. 0–64 mg/L)." (PMID 39001486, 2024). "On the other hand, renal cell carcinoma patients with strong infiltration of Foxp3+ lymphocytes had significantly higher CRP levels (elevated CRP with cut-off 5 mg/L)." (PMID 36980787, 2023). "The levels of CRP remained high at nearly 10 mg/dL during the clinical course of refractory renal cell carcinoma." (PMID 37415644, 2023). "In our case, the high levels of CRP for several months before the onset of the neurologic symptoms were considered due to advanced-stage renal cell carcinoma." (PMID 37415644, 2023). "Separately, a retrospective analysis suggested that CRP elevation was predictive of poor outcomes when incorporated into the International Metastatic Renal-Cell Carcinoma Database Consortium (IMDC) model for patients receiving axitinib." (PMID 34512646, 2021). "The value of CRP has been supported by numerous studies for both evaluation and treatment of renal cell carcinomas (RCC)." (PMID 34512646, 2021). "The serum CRP level is a generally accepted prognostic factor for patients with renal cell carcinoma." (PMID 32707675, 2020). "Our IL6 family cytokine profiling clearly illustrates that the acute phase reaction in patients with renal cell carcinoma possessed heterogeneity that was only partly reflected in the CRP level." (PMID 32707675, 2020). "The systemic levels of the acute phase protein CRP are a generally accepted prognostic factor for renal cell carcinoma." (PMID 32707675, 2020). "The prognostic impact of CRP shows that the acute phase reaction is important in renal cell carcinoma." (PMID 32707675, 2020). "We conducted a prior systematic review which found CRP to be prognostic of survival and treatment response specifically in gastrointestinal and renal cell carcinomas." (PMID 30138391, 2018). "For renal cell carcinoma, several publications demonstrated that high NLR, CRP/Alb ratios and PLRs were associated with a poor prognosis in RCC, respectively." (PMID 29890986, 2018).
renal cell carcinoma (continued). "In renal cell carcinoma, high CRP yielded a worse CSS (random-effect model; [HR] = 1.65, 95% [CI] = 1.29–2.10; p < 0.01) and OS (random-effects model; [HR] = 1.97, 95% [CI] = 1.58–2.44; p < 0.01)." (PMID 26235332, 2015). "In our review, CRP appeared to be a valuable prognostic predictor particularly in digestive tumors and renal cell carcinoma." (PMID 26717416, 2015). "C-reactive protein (CRP), a serum marker for systemic inflammation, has shown good prognostication in patients with renal cell carcinoma (RCC) and similar findings when combined with serum albumin levels in the modified Glasgow Prognostic Score." (PMID 25006517, 2014). "Previously, we reported that a high preoperative serum CRP level is an independent predictor of poor survival in patients with renal cell cancer." (PMID 23497335, 2013). "However, at least the baseline CRP levels were comparable (23 mg/L in renal cell carcinoma and 17 mg/L in our HNSCC collective)." (PMID 39001486, 2024). "It seems that for renal cell carcinoma, postoperative serum CRP titers and kinetics hold the most predictive values, and regarding bladder cancer, CRP has been linked to disease progression in non-muscle invasive bladder cancer and to the stage of and survival for muscle invasive bladder cancer." (PMID 37873776, 2023). "Indeed, in renal cell carcinoma, CRP had a higher area under the curve for predicting OS compared with albumin." (PMID 36096761, 2022). "For renal cell carcinoma, postoperative CRP levels and CRP kinetics hold the most predictive value." (PMID 34512646, 2021). "In addition, the results of this study also showed that CRP, tumor size, tumor necrosis, pathological type, surgical modes, AJCC stage and Fuhrman grade were also risk factors for postoperative death of patients with renal cell carcinoma." (PMID 39443568, 2024). "Several inflammatory markers have prognostic impact in renal cell carcinoma (RCC), including acute phase proteins, e.g., C-reactive protein and ferritin, but also derivatives of complete blood count such as monocytes, platelets, or lymphocytes levels." (PMID 34829506, 2021). "Preoperative SII and PNI, tumor size, tumor necrosis, surgical mode, pathological type, CRP, AJCC stage and Fuhrman grade are closely related to the postoperative prognosis of patients with renal cell carcinoma." (PMID 39443568, 2024). "Tsaur and his colleagues demonstrated that renal cells carcinoma of the chromophobe subtype had considerably reduced CX3CL1 gene expression relative to normal tissue, and that CX3CR1 and C-reactive protein were positively correlated." (PMID 37153002, 2023). "CCL22, CRP, ICAM1, IFNG, PDGFRA, TGFB1 and TNFSF11 have been confirmed to be involved in the malignant progression and metastasis of renal cell carcinoma through different biological mechanisms." (PMID 34187413, 2021). "Another study reported the case of a 40-year-old woman who was diagnosed with renal cell carcinoma (RCC) at 3 months after RT, and the levels of C-reactive protein (CRP), hemoglobin (Hb), and platelet (Plt values) were found to be normalized." (PMID 33297519, 2020). "In patients with renal cell carcinoma (RCC), serum C-reactive protein (CRP) level and the Glasgow Prognostic Score have prognostic significance." (PMID 24877032, 2014). "Tumor diameter and preoperative serum CRP levels are independent prognostic parameters in non-metastatic renal cell carcinoma; CRP thus serves as a marker of the acute phase reaction." (PMID 32707675, 2020). "The preoperative neutrophil-to-lymphocyte ratio (NLR), C-reactive protein/albumin ratio (CRP/Alb ratio) and platelet-to-lymphocyte ratio (PLR) have been demonstrated to predict the clinical outcome of various human cancer, including renal cell carcinoma(RCC)." (PMID 29890986, 2018).
renal cell carcinoma (continued). "Indeed, CRP albumin ratio (CAR), consisting of CRP and albumin, has been confirmed as a useful prognostic factor in many cancer types, including gastrointestinal, lung, and urological such as renal cell carcinoma." (PMID 37333829, 2023).
Hypokalemia (58 papers, 2003 to 2026). An abnormally decreased potassium concentration in the blood. "Furthermore, severe hypokalemia was associated with a median CRP value of 24.51 mg/dL (IQR: 9.23–28.71 mg/dL), significantly higher than the value recorded in the general group or patients with electrolyte disturbances in the context of severe MIS-C." (PMID 39451561, 2024). "Laboratory tests revealed severe hypokalemia (2.2 mmol/L), mild hypomagnesemia, hypophosphatemia, and markedly elevated CRP and procalcitonin." (PMID 41869153, 2026). "Laboratory abnormalities were only mentioned in one of the studies referenced; this patient exhibited hyperreninemia, hyperaldosteronism, and hypokalemia because of urinary retention, as well as an increase in CRP levels over time." (PMID 41037207, 2025). "Laboratory studies showed elevated C-reactive protein (CRP) at 80.5 mg/L and hypokalemia (K+ = 2.7 mmol/L), with preserved renal and hepatic function." (PMID 41503120, 2025). "Elevated blood levels for C-reactive protein (CRP) and lactate dehydrogenase were notable as was moderate hypokalemia and hypochloremia." (PMID 39840053, 2024). "The first reinfection case confirmed by genomic sequencing was reported from Hong Kong, with mild symptoms and normal laboratory findings except for elevated CRP and hypokalemia." (PMID 38005899, 2023). "Among these abnormal indices, hypokalemia, elevated CRP, and decreased lymphocytes were the 3 most prevalent indices among severe and critically ill patients." (PMID 32525548, 2020). "Patients with hypokalemia had significantly greater serum CRP." (PMID 38021540, 2023). "The initial venous lab values confirmed severe hypokalemia with potassium of 1.4 mM, normal sodium of 139 mM, normal magnesium, leukocytes and neutrophils elevated at 18.4 × 109/L and 16.0 × 109/L respectively, but with normal C-reactive protein (CRP) < 3 mg/L." (PMID 37122018, 2023). "Laboratory investigations were notable for hypokalemia, hypomagnesemia, mixed-pattern transaminitis, and elevated inflammatory markers (erythrocyte sedimentation rate (ESR) and C-reactive protein (CRP))." (PMID 40746791, 2025). "Investigations revealed a mildly elevated C-reactive protein (CRP) that peaked at 38 mg/L before normalizing, normal sodium levels, mild transient hypokalemia, and stable renal function." (PMID 41555989, 2025). "Laboratory examination showed severe hypokalemia, high white blood cell (WBC) counts, and C-reactive protein (CRP) levels." (PMID 39479075, 2024). "Laboratory tests showed an elevated white blood cell count; elevated levels of serum liver enzymes, blood urea nitrogen, creatinine, uric acid, C-reactive protein (CRP), and serum brain natriuretic peptide; hypoproteinemia; and hypokalemia." (PMID 30340526, 2018). "Furthermore, it has been reported that the clinical symptoms, CT images and blood test findings (e.g., hypokalemia, and high levels of ferritin, CPK and CRP) of COVID-19 pneumonia are similar to those of anti-MDA5 (+) CADM." (PMID 35069538, 2021). "Over half (56.5%; 182/322) had increased C-reactive protein (CRP); 38.8% (126/325) had elevated D-dimers; a quarter had leukocytopenia (25.2%; 82/325) or raised procalcitonin (PCT) (25.6%; 84/325); and 17.2% (56/325) had hypokalemia." (PMID 32573353, 2020).